TLR7 (toll like receptor 7)
Diseases named in the same sentence as TLR7 in open-access papers (continued):
Sharing a sentence is not in itself a finding about the gene and the disease.
Autoimmunity (continued). "The TLR7/8 innate immunity activation is not T1D specific, but is probably involved in the immune system modulation and autoimmunity." (PMID 32296701, 2020). "A new report found that the TLR trafficking chaperone UNC93B1 specifically limited the signaling of TLR7, but not TLR9, and prevented TLR7-dependent autoimmunity in mice." (PMID 32746880, 2020). "Yet, the male-specific protection from autoimmunity was not global as the lack of TLR7 resulted in an increase in salivary gland inflammation in male mice." (PMID 33322152, 2020). "The TLR trafficking chaperone UNC93B1, which prevents autoimmunity through the recruitment of syntenin-1, suppresses TLR7 specifically without affecting TLR9." (PMID 33371432, 2020). "However, autoimmunity and kidney pathology were both attenuated by crossing MRL/lpr mice to TLR7 KO mice or delayed by the administration of TLR7 antagonists to NZB/W mice." (PMID 31694920, 2019). "We report that TLR7, IL-6, and the adaptive immune system are essential for autoimmunity and glomerulonephritis but not for liver pathology in mice expressing the ubiquitin-binding–defective ABIN1[D485N] mutant." (PMID 31694920, 2019). "Because Bank1 is primarily expressed in B cells, our results imply that impairment of TLR7 signaling in B cells is not sufficient to trigger autoimmunity." (PMID 27228057, 2016). "Interestingly, Toll-like receptor 4 (TLR4) is the cognate receptor for LPS and its activation can induces up-regulation of other TLRs, such as TLR7 (the receptor for TMEV) and 9, known to be involved in autoimmunity." (PMID 19094215, 2008). "The corollary is that increased TLR7 trafficking in the absence of competition with TLR9 may worsen autoimmunity." (PMID 41178711, 2025). "While the results presented thus far indicate that the absence of NOX2 promotes B cell–specific, TLR7-dependent autoimmunity, whether this is a direct or indirect effect in the B cell could not be distinguished." (PMID 39042716, 2024). "Finally, in patients with ambiguous diagnoses of human autoimmunity featuring elevated IgG4 and sicca symptoms, TNIP1-mediated disease may be present and would pave the way for pathway-targeted treatments such as TLR7 and TBK1 inhibitors." (PMID 39060650, 2024). "TLR-7/8 and TLR-9 agonists are used in mRNA/DNA SARS-CoV-2 vaccinations as “adjuvants,” which may encourage the subset of ABC to produce autoantibodies and post-vaccination autoimmune disorders." (PMID 37896974, 2023). "Amongst the functional aberrations, a selectively enhanced responsiveness to TLR7/8 stimulation, but not to other TLR ligands, was noted, which might represent a contributing mechanism in the pathogenesis of STAT1 GOF-associated autoimmunity." (PMID 36172362, 2022). "Since TLR7 stimulation of Siglec-H-deficient pDCs in vitro does not lead to increased IFN-α responses, this is one explanation why these two types of RNA viruses did not induce autoimmunity in Siglec-H ko mice." (PMID 34497606, 2021). "However, our present data are in agreement with that showing that IL-17 are not a direct mediator of autoimmunity, but it controls microbiota-mediated vascular dysfunction induced by TLR7-activation." (PMID 34573058, 2021). "While Tlr7 is an X-linked gene that may escape X-linked inactivation, this does not explain the lack of protection from autoimmunity in female Tlr7 KO mice given that the Tlr7 KO NOD mice expressed no detectable TLR7 protein regardless of sex." (PMID 33322152, 2020). "However, UNC93B1 upregulation may also increase the responsiveness of TLR3, TLR7, TLR8, and TLR9 to their agonists, and conditions that lead to increased UNC93B1 expression may yield autoimmune disorders." (PMID 33597952, 2020). "Therefore, the evidence indicates that murine TLR7 and TLR8 possess unique functions in regulating autoimmunity and neuronal morphology, and although there is crosstalk between TLR7 and TLR8, they are not functionally redundant." (PMID 31684953, 2019).
Autoimmunity (continued). "Interestingly, TLR7 protein levels in plasma cells were only increased as a result of advanced autoimmunity and not the Tg7 itself." (PMID 31354711, 2019). "However, the absence of myeloid cell expansion and autoimmunity in IgH-/- mice in the presence of overexpression of TLR7 shows that the innate immune response role of B cells in the disease is fundamental." (PMID 27228057, 2016). "The interaction of intracellular OPN with the TLR7/9 pathway leading to the production of IFN-α in murine plasmacytoid dendritic cells and the presence of anti-dsDNA antibodies in OPN-expressing transgenic mice suggests the importance of this molecule to autoimmunity." (PMID 23343383, 2013). "Thus, TLR7 and TLR8, due to their localization on the X chromosome, might be overexpressed in females and could make them prone to type I IFN–driven inflammation and autoimmunity." (PMID 36633910, 2023). "Considering that dysfunction or dysregulation of TLRs, especially TLR4, TLR7, and TLR9, leads to a series of pathological conditions, we investigated whether ACK1 regulates the activation of the TLR signaling pathway and participates in the pathogenesis of inflammation and autoimmunity." (PMID 35669783, 2022). "Thus, TLR7 may play more complex disease-promoting and disease-protecting functions depending on the target organ in male NOD mice, but TLR7 deficiency did not alter autoimmunity in either SS or T1D manifestations in female NOD mice." (PMID 33322152, 2020). "Nevertheless, a study of TLR8−/− mice indicated that TLR8 regulates TLR7 expression and protects mice from autoimmunity, since TLR8−/− mice, but not TLR8−/− TLR7−/− mice, developed features of lupus-like syndrome." (PMID 30619338, 2018). "A role for TLR7 has not been evaluated in nonobese diabetic (NOD) mice, which spontaneously develop SS-like manifestations and are a well-established model for the study of SS-like lacrimal and salivary gland autoimmunity." (PMID 33322152, 2020).
psoriasis (156 papers, 2010 to 2026). An autoimmune condition characterized by red, well-delineated plaques with silvery scales that are usually on the extensor surfaces and scalp. "Aberrant activation of endosomal Toll‐like receptors TLR7–9 is recognized as a pathogenic driver in psoriasis." (PMID 40679079, 2025). "While various TLRs are implicated in psoriasis, only TLR7 expression was dramatically increased in keratinocytes following IMQ treatment." (PMID 40873769, 2025). "CMA deficiency in psoriasis leads to increased TLR7 levels, which, in turn, enhances TLR7-NF-κB signaling pathway activation, ultimately contributing to dysregulated keratinocyte proliferation, differentiation, and cytokine secretion." (PMID 40873769, 2025). "IMQ is a ligand of TLR7/8 and acts as a potent immune activator of DCs and causes them to mature, leading to psoriasis‐like skin lesions when applied to the skin." (PMID 35023281, 2022). "Topical application of IMQ, a toll-like receptor 7/8 agonist, on mouse skin causes immune cell accumulation, releasing cytokine and ROS, which damages dermal and epidermal tissues, leading to psoriasis-like skin changes." (PMID 34955833, 2021). "Dysregulation of TLR7/8/9, specifically TLR7 overexpression, has been closely associated with the pathology of psoriasis, a common inflammatory skin condition characterized by scaly reddish plaques caused by uncontrolled keratinocyte differentiation." (PMID 32660060, 2020). "We therefore studied the role of IRF5 in the development of psoriasis using a psoriasis-like inflammation model induced by imiquimod, a ligand for Toll-like receptor (TLR)-7 in IRF5-deficient mice." (PMID 32456211, 2020). "IMQ is a ligand for TLR7/8 that when applied topically to the skin, induces psoriasis-like inflammation in susceptible mice including BABL/c and C57BL/6." (PMID 31616442, 2019). "In IMQ‐induced psoriasis‐like mouse model of psoriasis, the selective activation of TLR‐7 in the skin CD11c+ DCs caused an increase in IL‐23 production and psoriasis‐like skin inflammation." (PMID 28377495, 2017). "Using a murine model of psoriasis induced by TLR7 agonist imiquimod (IMQ), we show that VISTA deficiency exacerbated psoriasiform inflammation." (PMID 28469254, 2017). "Given that IMQ-induced psoriasis-like skin inflammation and lesions are associated with activation of the TLR7-NF-κB (p65) signal, we then investigated whether CMA modulates IMQ-induced NF-κB activation in psoriasiform lesions." (PMID 40873769, 2025). "In vivo evidence from murine models suggested that treating psoriatic lesions with a TLR7 agonist could shift macrophages to a higher M1/M2 ratio, where excessive stimulation of TLR7 was associated with psoriasis pathogenesis." (PMID 39494336, 2024). "Finally, genome-wide association studies have identified hundreds of hypermethylated genes in psoriasis, and among them are immune-associated genes, such as TLR-7 (Toll-like receptor 7) and IRAK1 (interleukin 1 receptor associated kinase 1)." (PMID 35563264, 2022). "Hence, this research was aimed at further proving and evaluating the anti-psoriasis effect of Flos daturae as well as exploring the roles of the TLR7/8–MyD88–NF-κB and NLRP3 pathways in its underlying mechanisms." (PMID 31181689, 2019). "Notably, CXXC5 is highly expressed in plasmacytoid dendritic cells (pDCs) and is crucial for robust interferon responses to TLR7/9 stimulation (pDCs are one of the initiating immune cell types in psoriasis, as self-DNA/RNA induced pDC activation has been implicated in psoriatic plaque development)." (PMID 41328434, 2025). "TLR7 is expressed in eosinophils and regulates the secretion of inflammatory mediators, thereby promoting the migration, activation, and survival of neutrophils in psoriasis, which provides a possible mechanism that explains the causal relationship between eosinophils and psoriasis." (PMID 36865550, 2023).
psoriasis (continued). "Thus, it may be hypothesized that Hsp70 not only interacted with Treg-associated TLR2, but also directly interfered as damage-associated molecular pattern with psoriasis-specific signaling of TLR7/8." (PMID 33708208, 2021). "Although the direct action of MHP1-AcN on IL-23 and its effects in the IL-23-induced psoriasis model need further studies, one of the preventative effects of MHP1-AcN on psoriasis may be associated with the inhibition of TLR7/8-induced IL-6 and IL-23 expression." (PMID 31659208, 2019). "Further studies have shown that application of a TLR7 agonist (Imiquimod) to the skin of humans and mice can initiate psoriatic lesions that are dramatically worsened on an IL-36RA null background, whereas imiquimod-induced psoriasis is completely abolished in IL-36R-deficient mice." (PMID 29515113, 2018). "While endosomal Toll-like receptors (TLRs), particularly TLR7, are key drivers of psoriatic exacerbations, the regulatory mechanisms governing TLR7 activity in psoriasis remain incompletely understood." (PMID 41684130, 2026). "To establish a mouse model of psoriasis, we applied treatment with IMQ, a reagent known to induce psoriasis-like conditions in mice via TLR7/8 activation, daily for a week on the shaved backs of mice." (PMID 39993340, 2025). "In a mouse model of psoriasis induced by the Toll-like receptor 7 (TLR7) agonist named imiquimod (IMQ), it was shown that IL-17A-producing Vγ4Vδ4 T cells exhibit similarities, suggesting oligoclonal expansion or a common fetal origin of these cells." (PMID 40276509, 2025). "Conversely, the IMQ-induced psoriasis paradigm primarily stimulates the IL-1 and TLR7 pathways, which, while contributing to inflammation, vary from the main IL-23/Th17-mediated inflammation reported in patients." (PMID 40667480, 2025). "This phenomenon of inducing psoriasis is established in preclinical settings, where imiquimod is widely used as a standard drug that activates the immune system via toll-like receptor 7 and thus pro-inflammatory cytokine cascade." (PMID 40284473, 2025). "Imiquimod (IMQ) is a modifier of safety response that acts as a TLR-7/8 agonist, and the topical application in mice induces psoriasis-like dermatitis." (PMID 40343294, 2025). "The scaffold function of IRAK4 plays a pivotal role not only in TLR4-mediated ALI, but also in TLR7/8-mediated psoriasis and TLR7/9-mediated SARS-CoV-2 infection." (PMID 40771916, 2025). "This suggests a critical role for TLR7 signalling in psoriasis, and warrants future studies on the link between post-translational modifications of TLR7 and c-Rel activation." (PMID 39586195, 2024). "In this study, we studied the specific role of NF-κB c-Rel in TLR7 signalling in DCs and its functional relevance in psoriasis." (PMID 39586195, 2024). "Recent papers have also reported that TLR7 signalling through the NF-κB pathway plays a key role in psoriasis disease progression." (PMID 39586195, 2024). "This study on the role of TLR7/c-Rel signalling axis in DC mediated inflammation during psoriasis provides a comprehensive view of an essential molecular mechanism involved in psoriatic disease pathogenesis." (PMID 39586195, 2024). "In this study, we show that NF-κB c-Rel is a transcriptional regulator of TLR7-induced inflammatory signalling in DCs which is critical in psoriasis-like skin inflammation." (PMID 39586195, 2024). "Inflammation in psoriasis can be triggered following Toll-like Receptor 7 (TLR7) signalling in dendritic cells (DCs), and c-Rel is a critical regulator of DC function." (PMID 39586195, 2024). "Taken together, these data suggest that c-Rel has a critical transcriptional regulatory role in TLR7-induced inflammatory signalling in DCs during psoriasis." (PMID 39586195, 2024). "In psoriasis, LL-37 not only directly promotes the gene expression related to psoriasis but also activates TLR7/8, which further enhances this gene expression." (PMID 38606161, 2024).
psoriasis (continued). "c-Rel is highly expressed in lesional skin of patients with psoriasis and TLR7-induced psoriatic lesions in mice." (PMID 39586195, 2024). "Further confirming that this signalling axis is relevant in DCs during psoriasis in vivo, we found a substantial increase in the colocalisation of TLR7, c-Rel, and CD11c in the dermis of IMQ-treated dorsal skin samples of WT mice." (PMID 39586195, 2024). "The elucidation of the TLR7/c-Rel signalling axis in psoriasis pathogenesis warrants strategies that inhibit c-Rel activation to be a possible therapeutic approach for psoriasis treatment." (PMID 39586195, 2024). "Elucidating this current gap in mechanistic insight on the TLR7/c-Rel axis is key in developing better therapeutic strategies for treating psoriasis." (PMID 39586195, 2024). "IMQ, a Toll-like receptor 7/8 agonist, can induce or exacerbate psoriasis-like lesions mimicking many natural ligands that are involved in the induction of psoriasis." (PMID 39273201, 2024). "Imiquimod, a toll-like receptor 7 (TLR7) agonist, induces skin inflammation resembling human psoriasis via activation of the interleukin 23 (IL-23)/interleukin 17 (IL-17) axis." (PMID 39327628, 2024). "IMQ is a Toll-like receptor 7/8 ligand agonist that induces psoriasis-like dermatitis in mice, closely resembling human psoriasis." (PMID 39109246, 2024). "Our findings suggest that NF-κB c-Rel plays a critical role in TLR7-mediated inflammation in DCs and warrants consideration of strategies to suppress c-Rel activation as a therapeutic approach in the clinic for psoriasis treatment." (PMID 39586195, 2024). "TLR7, as a member of pattern recognition receptors, takes part in many immune-related skin diseases, including psoriasis, atopic dermatitis and so on." (PMID 37780385, 2023). "For example, psoriatic keratinocytes generate self-RNA, binding to TLR7 in myeloid dendritic cells to amplify the inflammatory circuits in psoriasis." (PMID 37780385, 2023). "Imiquimod is considered a TLR7/8 agonist, which can induce and intensify psoriasis in rat model via the activation of IL-23/IL-17A axis." (PMID 37010718, 2023). "Then use the prepared diosmin nanocrystals gel topically in 3 different concentrations to evaluate its efficacy in alleviating IMQ induced psoriasis in rats via modulating TLR7,8/NF-κB/micro RNA-31, AKT/mTOR/P70S6K milieu and Tregs/Th17 balance." (PMID 37010718, 2023). "Previous studies illustrated that the inhibition of activation of TLR-7/NF-κB pathway in IMQ-induced psoriasis in mice by rhododendrin played an important role in the therapy of psoriasis." (PMID 37010718, 2023). "IMQ is a toll-like receptor-7 and -8 (TLR7 and 8) ligand and can exacerbate psoriasis development in patients, possibly acting via the IL-17/IL-23 axis." (PMID 37900099, 2023). "Abnormal activation of toll like receptor 7/8 (TLR7/8) is proved to be involved in the pathogenesis of psoriasis." (PMID 37010718, 2023). "IMQ rapidly triggers psoriasis development by activating TLR7 on dendritic cells to produce pro-inflammatory cytokines, including IL-23 and IL-1β, without directly providing specific antigens to be presented through MHCI and MHCII." (PMID 37594540, 2023). "TLR7 is expressed on DCs and is important in psoriasis development as an intracellular TLR that mediates viral nucleic acid recognition." (PMID 37160878, 2023). "The co-network indicated that CXCL16 positively correlated with TLR7 expression and was involved in the psoriasis process." (PMID 37160878, 2023). "A TLR7 agonist, imiquimod, induces clinical and histological changes characteristic of human psoriasis, including epidermal thickening, scaling and erythema." (PMID 37215725, 2023). "Rutaecarpine inhibited IMQ-induced psoriasis-like dermatitis by inhibiting the NF-κB and TLR7 pathways in mice." (PMID 37160878, 2023). "In this study, IMQ was used for the construction of a psoriasis-like dermatitis model in mice for its TLR7/8 activation effect." (PMID 35966027, 2022).